BEND6 (BEN domain containing 6)
Description:
Acts as a corepressor of recombining binding protein suppressor hairless (RBPJ) and inhibits Notch signaling in neural stem cells, thereby opposing their self-renewal and promoting neurogenesis.
Synonyms: C6orf65; FLJ30162; bA203B9.1
Tractability: Small molecule: a structure with a bound ligand is known. Antibody: the Human Protein Atlas places it where antibodies can reach.
Gene: Protein-coding gene on chromosome 6 (56,954,924 to 57,027,832, forward strand). Ensembl gene ENSG00000151917.
Subcellular location: Nucleus
Subcellular location (Human Protein Atlas): Nucleoplasm; Plasma membrane
Gene Ontology:
Molecular function: transcription corepressor activity; chromatin binding; DNA binding
Biological process: negative regulation of Notch signaling pathway; positive regulation of neuron differentiation; negative regulation of DNA-templated transcription; regulation of gene expression
Cellular component: nucleus
Genetic constraint (gnomAD): Loss-of-function variants: 23 observed, 30.02 expected, observed/expected ratio (o/e) 0.77, 90% interval 0.55 to 1.09. The upper end of that interval is the gene's LOEUF score, 1.09, which puts it in group 4 of 6, group 1 being the genes least tolerant of losing a copy. Missense variants: 292 observed, 309.62 expected, observed/expected ratio (o/e) 0.94, 90% interval 0.86 to 1.04. Synonymous variants: 109 observed, 107.06 expected, observed/expected ratio (o/e) 1.02, 90% interval 0.87 to 1.19.
Homologues: Orthologues: chimpanzee BEND6 (99% identical), macaque BEND6 (97% identical), dog BEND6 (96% identical), rabbit BEND6 (94% identical), pig BEND6 (92% identical), rat Bend6 (84% identical), mouse Bend6 (83% identical), guinea pig BEND6 (72% identical).